Y_RNA (Y RNA )
Gene: Miscellaneous RNA gene on chromosome 1 (185,257,911 to 185,258,015, reverse strand). Ensembl gene ENSG00000206640.
Homologues: Orthologues: chimpanzee Y_RNA (99% identical), macaque Y_RNA (94% identical), guinea pig Y_RNA (83% identical). Paralogues in human: Y_RNA (88% identical), RNY3 (87% identical), Y_RNA (87% identical), Y_RNA (86% identical), RNY3P16 (85% identical), Y_RNA (85% identical), RNY3P1 (84% identical), Y_RNA (84% identical), Y_RNA (83% identical), RNY3P11 (82% identical), RNY3P9 (82% identical), Y_RNA (82% identical), and 93 more.